ABCG2 (ATP binding cassette subfamily G member 2 (JR blood group))
Diseases named in the same sentence as ABCG2 in open-access papers (continued):
Sharing a sentence is not in itself a finding about the gene and the disease.
lung carcinoma (continued). "Thus, Liu and coworkers showed that lung cancer cells surviving to cisplatin treatment are enriched in CD133+ cells, displaying multiple drug resistance mainly related to expression of the drug transporter ABCG2." (PMID 30060526, 2018). "Finally, we show that the H460 SP cells preferentially express ABCG2 as well as SMO, a critical mediator of the Hedgehog (HH) signaling, which seems to play an important role in H460 lung cancer cells as its blockage using Cyclopamine greatly inhibits cell-cycle progression." (PMID 22428030, 2012). "We found expression of ABCG2 and Sca-1 to be upregulated in the SP cells isolated from D121 lung cancer cells when compared with that of non-SP derived from these same cancer cells as detected by flow cytometry, by immunohistochemical fluorescence histology staining and RT–PCR." (PMID 21468047, 2011). "Colon and lung cancer cells with and without ABCG2 overexpression were treated with FL118 in the presence and absence of Ko143, an ABCG2-selective inhibitor, or alternatively by genetically modulating ABCG2 expression." (PMID 25928015, 2015). "However, the relationship between YAP1 and ABCG2 and YAP1 regulation of cancer cell side population in lung cancer have never been reported." (PMID 27911857, 2017).
colon carcinoma (135 papers, 2008 to 2026). "ABCG2 expression was significantly associated with microsatellite instability and patient weight in colon carcinoma, and with anatomical organ subdivision, patient age and population type in rectum adenocarcinoma." (PMID 37445716, 2023). "Several proteins involved in drug efflux belonging to ABC family transporters: ABCB1 (P-glycoprotein-Pgp), ABCC1 (MDR-associated protein 1-MRP1), and ABCG2 (breast cancer resistance protein-BCRP) are increased in colon cancer." (PMID 36009495, 2022). "In ABCG2 gene, two additions of C and T were found in intron 8 most of the studies have focused on association of ABCG2 gene with colon cancer and have found novel mutations." (PMID 37092084, 2022). "In human colon cancer cell, ABCG2 is known as main cause of resistance to drug such as SN-38 which is used for chemotherapy in colon cancer." (PMID 26149077, 2015). "Besides Sox2 and ALDH, expression of several other surface proteins, such as CD44, CD133, Lgr5, CD24, EpCAM and ABCG2, has been associated with stemness features in the context of colon cancer." (PMID 32927726, 2020). "It is therefore possible that part of the mechanism behind the increased susceptibility of stem-like colon cancer cells to chemotherapy upon ERK5 inhibition could involve ABCG2 repression." (PMID 30774996, 2019). "This study aimed to evaluate the potential effects of agmatine on cell viability, migration, invasion, apoptosis, and the expression of the ABCB1, ABCC1, and ABCG2 genes in the Caco-2 colon cancer cell line." (PMID 41557172, 2026). "Overexpression of NFIB in colon carcinoma Caco-2/TC7 cells caused significant NFIB-dependent inhibition of ABCB1 and ABCG2 gene expression." (PMID 40554316, 2025). "The high expression levels of PMI and ABCG2 in drug-resistant tissues of colon cancer were confirmed using immunohistochemistry, immunofluorescence, and western blot analyses." (PMID 38576495, 2024). "As another example, 3-methylcholanthrene (3MC) upregulates ABCG2 expression in colon cancer LS174T cells via the activation of AHR which binds to the AHR response element 5 within ABCG2 promoter region and thus activate the transcription of ABCG2." (PMID 39114355, 2024). "Consisting of miR-519c binding sites within the 3′UTR, ABCG2 was showed to be repressed by miR-519c in the S1 colon cancer cells." (PMID 39114355, 2024). "The causes of resistance to clinical chemotherapy are complex and varied, and the “seed” theory, in which ABCG2 plays an important role, has received much attention for colon cancer." (PMID 38576495, 2024). "ABCG2, an important marker for colon cancer stem cells, is highly expressed in drug-resistant cells." (PMID 38576495, 2024). "Given the important role of ABCG2 in stem cell formation and drug resistance in colon cancer, effects of changes in its expression deserve to be explored." (PMID 38576495, 2024). "The results of the present study suggest that LBP reverses drug resistance in colon cancer cells by reducing ABCG2 expression." (PMID 38576495, 2024). "The relationship between AP3M2 and ABCG2 was positive in colon cancer (r = 0.12) and rectal cancer (r = 0.18)." (PMID 38177168, 2024). "Anticancer drugs, such as 5-FU, can activate the IRE1α-XBP1 pathway to induce the expressions of ABCB1, ABCC1 and ABCG2 in colon cancer cells." (PMID 37790807, 2023). "The side population of colon cancer cell line SW480 exhibits high ABCG2 mRNA and transporter expression, accompanied by high CD44 mRNA and protein levels, regarded as a key marker of solid tumour CSCs." (PMID 37445716, 2023). "One study in the S1 colon cancer cell line revealed that a miRNA binds to the 3′ UTR of ABCG2, thereby decreasing expression." (PMID 37218814, 2023). "Using our novel framework, several ABCG2 regulator genes are discovered as potential predictive markers in microsatellite stable stage III colon cancer samples." (PMID 35996085, 2022).
colon carcinoma (continued). "VKNG-1 has been identified as a novel ABCG2 inhibitor that has a favorable preclinical toxicity profile that can restore the in vitro and in vivo efficacy of chemotherapeutic drugs that are ABCG2 substrates in drug-resistant colon cancers." (PMID 34572902, 2021). "VKNG-1, a phenyltetrazole analogue selectively inhibits the ABCG2 transporter and reverses resistance to standard anticancer drugs both in vitro and in vivo in ABCG2-overexpressing colon cancers." (PMID 34572902, 2021). "VKNG-1, at 6 μM, selectively inhibited ABCG2 transporter and sensitized ABCG2-overexpressing drug-resistant cancer cells to the ABCG2 substrate anticancer drugs mitoxantrone, SN-38, and doxorubicin in ABCG2-overexpressing colon cancers." (PMID 34572902, 2021). "The cell lines used in this study were NSCLC NCI-H460 and its drug-selected subline, NCI-H460/MX20, which overexpresses wild-type (WT) ABCG2 and colon cancer cell line S1, as well as its drug-selected subline, S1-M1-80, which overexpresses R482G mutant ABCG2." (PMID 31940916, 2020). "One of the main findings of this study was that poziotinib concentration-dependently increased the efficacy of mitoxantrone and SN-38 in ABCG2-overexpressing S1-M1-80 colon cancer cells and ABCG2 transfected HEK293/ABCG2 cells." (PMID 33158067, 2020). "Previous study has established a mitoxantrone-selected drug-resistant S1-M1-80 subline from human S1 colon cancer cell line and suggested ABCG2 overexpression as the major resistance mechanism in the resistant subline." (PMID 33692943, 2020). "Overall, our results indicate that, in part, poziotinib reverses MDR in S1-M1-80 and SW620/Ad300 colon cancer cell by inhibiting the efflux of ABCG2 and ABCB1 substrates, respectively." (PMID 33158067, 2020). "In this study, we report that in vitro, poziotinib can antagonize both ABCB1- and ABCG2-mediated MDR at 0.1–0.6 μM in the human colon cancer cell lines, SW620/Ad300 and S1-M1-80." (PMID 33158067, 2020). "In this study, we determined the efficacy of poziotinib to overcome ABCG2- or ABCB1-mediated MDR in colon cancer cells and in HEK293 cells." (PMID 33158067, 2020). "Hypermethylation of the ABCG2 promoter has been reported for colon cancer, multiple myeloma, EBV gastric cancer, and acute leukemia." (PMID 33066132, 2020). "Increased miRNA expression, especially miR142-3p was expressed in colon cancers cells after AC treatment, and ABCG2 genes over-expression is importantly correlated with multidrug resistance mechanism associated with tumorigenic stem cells." (PMID 31349708, 2019). "Immunohistochemistry data showed that ALDH1 and ABCG2 levels were higher in colon cancer in comparison with benign tumors." (PMID 31516883, 2018). "Immunohistochemistry showed that ALDH1 and ABCG2 expression levels increased to 80% and 76%, respectively in colon cancer tissues as compared to 33% and 28% in benign tumor tissues." (PMID 31516883, 2018). "In this study, we evaluated the expression levels of ALDH1 and ABCG2 in Iraqi patients with colon cancer and/or benign colon tumors." (PMID 31516883, 2018). "Our results demonstrated that the levels of drug transporter proteins such as MDR1, MRP1, and ABCG2 were up-regulated in colon cancer cells treated with DOX and fidarestat treatment prevented the DOX-induced increase in the MDR1, MRP1, and ABCG2." (PMID 28600556, 2017). "More importantly, the separation of the survival curves among the patients receiving irinotecan pointed to a predictive utility of ABCG2 mRNA measurement in the adjuvant irinotecan treatment of patients with colon cancer." (PMID 28880238, 2017). "Recently, we published an exploratory study of ABCG2 mRNA expression (dichotomized by medium value) in 580 evaluable patients with colon cancer stage III enrolled in the adjuvant PETACC-3 prospective randomized study." (PMID 28880238, 2017).
colon carcinoma (continued). "In our previous study, SP cells were isolated from gallbladder carcinoma cell lines and colon cancer cell lines with high ABCG2 expression, and this small population of cells was able to self-renew and differentiate into both SP cells and non-SP cells." (PMID 28212529, 2017). "It has been found that ABCG2 expression is associated with cancer resistance to SN38 and it has also been shown that ABCG2 over-expressed in colon cancer samples with SN38 resistance." (PMID 28948511, 2017). "ABCG2 (BCRP/MXR) is the first half transporter in the ABC transporter family, it has been found in mitoxantrone (MX) selected human colon carcinoma cell line S1-M1-80, so giving ABCG2 the name of mitoxantrone resistant protein (MXR)." (PMID 26556876, 2015). "SW480 and HT29 cells were selected, which showed the lowest and highest ABCG2 expression level, respectively, among the tested colon cancer cells." (PMID 26149077, 2015). "In colon cancers, a study reported that the expression of ABCG2 correlated with the shortened patient survival." (PMID 26149077, 2015). "ABCG2 has been described as directly involved in acquired resistance to SN-38 in colon cancer cells." (PMID 25890497, 2015). "In this study, we demonstrated that ABCG2 plays a main role in drug resistance related to PDT in colon cancer cell." (PMID 26149077, 2015). "It is expressed in colon cancer cells resistant to MX, thereby giving ABCG2 the name MX resistant protein (MXR)." (PMID 24626598, 2014). "This study attempted to understand the regulation of ABCG2 by the various adverse growth conditions within the tumor microenvironment in colon carcinoma cell lines." (PMID 22778999, 2012). "The ABCG2 mRNA expression was evaluated in three human colon carcinoma cell lines (HCT-116, S1 and its resistant subline S1M1-80) after the pretreatment with glucose depletion, 2-DG, acidic pH and hypoxia." (PMID 22778999, 2012). "Taken together, our work demonstrated that JNK1/c-jun signaling pathway was involved in ABCG2-mediated multidrug resistance in colon cancer cells." (PMID 22870247, 2012). "Definitely, inhibition of the JNK1/c-jun pathway is useful for reversing ABCG2-mediated drug resistance in HCPT-resistant colon cancer cells." (PMID 22870247, 2012). "In the present study, we systematically investigate the potential role of the c-Jun NH2-terminal kinase (JNK) signal pathway in ABCG2-induced multidrug resistance in colon cancer." (PMID 22870247, 2012). "The positive correlation of expression of β-catenin and ABCB1 was also shown in side-population colon cancer cells, however, ABCG2 expression was also found to be dependent on β-catenin levels." (PMID 22460269, 2012). "The data revealed that hypoxia, glucose deprivation, and acidosis can all upregulate ABCG2 in the two parental colon cancer cell lines and apparently leading to multidrug resistance." (PMID 22778999, 2012). "In our study, we unveil an elevated expression of ABCG2 in colon cancer tumour spheres, which is also anticipated to have a critical role in drug resistance of colon CSCs." (PMID 20332776, 2010). "Consistent with their stem cell properties, real-time reverse transcriptase PCR analyses demonstrate expression of ABCC1 and ABCG2 genes in CD133+ colon cancer tumour spheroid cells." (PMID 20332776, 2010). "Another mRNA ABCG2 (logFC(ABCG2)=−5.075) was expressed less in colon cancer." (PMID 39202109, 2024). "Therefore, the present study investigated whether LBP could affect the expression levels of ABCG2 as well as the Bcl-2 protein family and explore possible mechanisms underlying these effects in order to provide a theoretical basis for clinical treatment of colon cancer." (PMID 38576495, 2024). "Although it was pointed out that ABCG2 is related to colon cancer, the differential expression of this gene plays an important role in the photodynamic therapy of colon cancer, and studies have shown that there is still controversy over the expression of ABCG2." (PMID 39202109, 2024).
colon carcinoma (continued). "Also, vatalanib sensitized the colon cancer cell lines to SN-38, a substrate of P-gp and ABCG2, under hypoxic growth conditions." (PMID 38269272, 2023). "Moreover, elevated levels of ABCG2 were correlated with chemotherapy resistance in colon cancer cells." (PMID 37751451, 2023). "A potential mechanism of these miR-142-3p mimics is the suppression of tumor growth by down-regulating the expression of CD133, leucine-rich repeat containing G protein-coupled receptor 5 (LGR5), and ATP-binding cassette subfamily G member 2 (ABCG2) in colon cancer cells." (PMID 33600577, 2021). "Therefore, in this manuscript, experiments are conducted to determine the reversal mechanism of VKNG-1 in anticancer drug resistance in vitro and in a tumor xenograft model in drug-resistant ABCG2-overexpressing colon cancers." (PMID 34572902, 2021). "We first noticed that citarinostat was significantly more cytotoxic to the parental human KB-3-1 epidermal cancer cells and the parental human S1 colon cancer cells than to the respective ABCB1-overexpressing variant KB-V-1 (R.F = 15) and ABCG2-overexpressing variant S1-M1-80 (R.F = 21) cells." (PMID 33807514, 2021). "The combination of 30 mg/kg oral VKNG-1 with a dose of 10 mg/kg i.p. of irinotecan significantly reduced tumor size, growth rate, and tumor volume in mice with ABCG2-overexpressing tumor xenografts, compared to either drug alone in ABCG2-overexpressing colon cancers." (PMID 34572902, 2021). "Overall, our results suggest that VKNG-1 may, in combination with certain anticancer drugs, represent a treatment to overcome ABCG2-mediated MDR colon cancers." (PMID 34572902, 2021). "More recently, we have published on the association between ABCG2 mRNA expression and irinotecan effects in the PETACC-3 prospective randomized clinical trial, where patients with stage III colon cancer were randomized to adjuvant 5FU/LV or 5FU/LV and irinotecan." (PMID 32708825, 2020). "The results of our study indicate that poziotinib increases the efficacy of chemotherapeutic drugs (i.e., reverses MDR) in MDR colon cancer cells by interacting with and affecting the efflux activity of the ABCG2 and ABCB1 transporters and the protein expression level of the ABCG2 transporter." (PMID 33158067, 2020). "The reversal of MDR in colon cancer cells overexpressing the ABCG2 or ABCB1 transporters could result from poziotinib inhibiting the efflux or transport function." (PMID 33158067, 2020). "When these drugs have been tested in regular clinical phase II trials in patients with metastatic and irinotecan resistant colorectal cancer, they can be taken into randomized clinical testing including Stage III colon cancer patients with high ABCG2 expression." (PMID 32326511, 2020). "Thus, the results indicated that poziotinib is reversing MDR in S1-M1-80 and SW620/Ad300 colon cancer cells by inhibiting the ABCG2 and ABCB1 transporter." (PMID 33158067, 2020). "This could, in part, explain why poziotinib was more potent in reversing the resistance to the ABCB1 substrates, paclitaxel and doxorubicin, than the ABCG2 substrates, mitoxantrone and SN-38 in the colon cancer cells, although this remains to be elucidated." (PMID 33158067, 2020). "The involvement of ABCG2 in irinotecan resistance was corroborated in clinical samples from colon cancer patients demonstrating increased levels of the ABCG2 mRNA in hepatic metastases after irinotecan-based chemotherapy in comparison with irinotecan-naive metastases." (PMID 32456134, 2020). "Similarly, human colon cancer cells with acquired resistance to irinotecan have an increased expression of ABCG2 in comparison with sensitive cells." (PMID 32456134, 2020). "It is possible that poziotinib’s increase in the efficacy of the chemotherapeutic drugs in the drug-resistant colon cancer cells could be due to downregulating the expression level of the ABCG2 and ABCB1 transporter protein." (PMID 33158067, 2020).